MIR944 (microRNA 944)
Synonyms: hsa-mir-944; MIRN944; mir-944
Gene: MicroRNA gene on chromosome 3 (189,829,922 to 189,830,009, forward strand). Ensembl gene ENSG00000216058.
Gene Ontology:
Biological process: miRNA-mediated post-transcriptional gene silencing
Cellular component: RISC complex
Homologues: Orthologues: chimpanzee ptr-mir-944 (100% identical), macaque mml-mir-944 (94% identical).
Diseases named in the same sentence as MIR944 in open-access papers:
MIR944 is named in the same sentence as 1 disease in open-access papers, as found by Europe PMC text mining. Sharing a sentence is not in itself a finding about the gene and the disease. The quoted sentences say what the papers report.
melanoma (1 paper, 2015). A malignant, usually aggressive tumor composed of atypical, neoplastic melanocytes. "In keratinocytes, the region encompassing the MIR944 promoter has a relatively open chromatin structure, in contrast to the corresponding region in WM266-4 melanoma cells, which do not express ΔNp63 mRNA and miR-944." (PMID 26202967, 2015).